IL1A (interleukin 1 alpha)
Diseases named in the same sentence as IL1A in open-access papers (continued):
Sharing a sentence is not in itself a finding about the gene and the disease.
osteoarthritis (21 papers, 2008 to 2025). A noninflammatory degenerative joint disease occurring chiefly in older persons, characterized by degeneration of the articular cartilage, hypertrophy of bone at the margins and changes in the synovial membrane. "Some of the hyaluronan export inhibitors have already been applied to prevent hyaluronan over-production and proteoglycan loss in IL-1α activated chondrocyte cell cultures, in cartilage organ cultures and in an animal model of osteoarthrosis." (PMID 18205921, 2008). "The mechanisms relating reduced IL-1α and adiponectin levels with joint degeneration remain unclear as osteoarthritis severity and extracellular matrix degradation is associated with increased levels of both IL-1α and adiponectin." (PMID 20604941, 2010). "This includes lutikizumab (anti-IL1a and IL1b) for osteoarthritis, and COVA322, a bispecific TNF/IL17A antibody fusion protein studied in phase 1/2 in patients with stable chronic moderate-to-severe plaque Pso (stopped for safety reasons)." (PMID 40529150, 2025). "The inflammation in osteoarthritis is regulated by biochemical substances, such as prostanoids, cytokines (IL-1α, IL-1β, TNF-α, PGE2), proteases, and ROS produced by synoviocytes and chondrocytes." (PMID 39204123, 2024). "Consistently, chondrocytes in osteoarthritis cartilage displayed an increase in PIEZO1 expression upon IL-1α stimulation." (PMID 38627713, 2024). "Biomarkers of inflammation and cartilage degradation related to osteoarthritis were also analyzed, and significant differences were found only for IL1-α, which was decreased in the MMedDietD group." (PMID 37885010, 2023). "Although IL-1β was used in the induction of inflammation in the osteoarthritis study, that cytokine can bind to the same receptor as IL-1α and thereby can be thought to evoke similar inflammatory conditions." (PMID 35661979, 2022). "Interleukin-1 receptor antagonist protein (IL-1ra or IRAP), is a potent anti-inflammatory protein that binds type IL-1 receptors and competitively inhibits IL-1α and IL-1β, both of which initiate a pro-inflammatory cascade in osteoarthritis through activation of NF-κB." (PMID 30895181, 2019). "Previous results suggest that IL-1α/β could be an important mediator involved in the pathogenesis of osteoarthritis (OA)." (PMID 28659793, 2017).
pneumonia (21 papers, 2011 to 2025). An acute, acute and chronic, or chronic inflammation focally or diffusely affecting the lung parenchyma, caused by an infection in one or both of the lungs (by bacteria, viruses, fungi, or mycoplasma.). "Lung neutrophils from mice with pneumonia showed increased expression of genes that encode a number of mediators, including the important pro-inflammatory cytokines IL-1α, IL-6, TNF and CXCL1 (KC)." (PMID 28900269, 2017). "When comparing pneumonia-affected sheep to resistant ewes, the IL-1α, IL1B, IL6, and TNF-α genes were markedly upregulated." (PMID 40711280, 2025). "Accordingly, in our work, we observed that key inflammatory markers (IL-6, TNF-α, IL-8, IL-1α, and IP-10) were elevated in serum from hospitalized women due to severe features, such as pneumonia." (PMID 36016660, 2022). "We also showed that the inflammatory cytokines such as IL-1α, IL-6, and IL-12 p40 in Mp-induced pneumonia are dependent on the TLR2 in mice." (PMID 34937175, 2021). "Reduces levels of B lymphocytes, CD8+ proportion, IL-1α, IL-1β, IL-2, IgM, IgG, etc., reduces quality of thymus, spleen and lung of pneumonia mice, and increase CD4+/CD8+ and NK cell proportion." (PMID 32848729, 2020). "Further studies found that SFJDC had a significant immune regulatory function, reducing levels of B lymphocytes, CD8+ cells, interleukin-1α (IL-1α), IL-1β, IL-2, IgM, and IgG to improve lung function in mice with pneumonia." (PMID 32848729, 2020). "Further investigations are needed to elucidate the role of IL-1α in HAdV-55-induced inflammation especially pneumonia." (PMID 30787914, 2019). "In our opinion, this is the first study to identify SNPs in antioxidant (SOD1, CAT, GPX1, NOS, HMOX1, and NQO1) and immunological (IL-1α, IL1B, IL6, TNF-α, IL10, LFA-1, CR2, IL17, IL13, DEFB123, SCART1, and ICAM1) genes as potential suspects for pneumonia resistance/susceptibility in Barki ewes." (PMID 40221769, 2025). "IL-33 provides protection against pneumonia-induced acute lung injury, potentially mediated through increased eosinophilia and lower neutrophil recruitment, while the role of IL-1α (in comparison to IL-1β) are poorly understood, but likely act through liver-dependent mechanisms." (PMID 36829255, 2023). "Using PCR-DNA sequence verdicts, the IL-1α (356-bp), IL-1β (423-bp), IL-6 (384-bp), TNFα (490-bp), IL-10 (306-bp), IFN-γ (321-bp), PRDX6 (434-bp), ATG7 (416-bp), NDUFS6 (405-bp), and NOX4 (396-bp) genes were found to have different SNPs in the amplified DNA bases linked to pneumonia." (PMID 40711280, 2025). "Our investigation used a PCR-DNA-sequencing procedure to illustrate the difference in immunological (IL-1α, IL1B, IL6, TNF-α, IL10, and IFN-γ) and antioxidant (PRDX6, ATG7, NDUFS6, and NOX4) genes in calves with pneumonia and healthy calves." (PMID 40711280, 2025). "The genes IL-1α, IL1B, IL6, TNF-α, IL10, IFN-γ, and NOX4 had significantly greater gene expression levels in pneumonia-affected calves compared to the CON group." (PMID 40711280, 2025). "In sheep with pneumonia, CAT (0.35 ± 0.11) was the most downregulated, whereas IL-1α (2.66 ± 0.08) was the most upregulated." (PMID 40221769, 2025). "It has a therapeutic impact on pneumonia model rats by reducing B lymphocytes, CD8+ ratio, and elevated levels of IL-1α, IL-1β, IL-2, IL-10, TNF-α, IFN-α, IFN-γ, IgM, IgG, CD4+/CD8+, and NK cells." (PMID 36388945, 2022). "In fact, these viruses markedly induced the expressions of pro-inflammatory cytokines and chemokines including IL6, IL1α, IL1β, TNFα, IFNγ and CCL5 in the lungs, resulting in severe pneumonia." (PMID 21826229, 2011). "The importance of IL-1α as mediator of lung inflammation has recently been shown in the randomized clinical trial SAVE-MORE; patients with pneumonia by the novel coronavirus SARS-CoV-2 were treated for 10 days with anakinra which is blocking the biological action of both IL-1α and IL-1β." (PMID 37680472, 2023).
pneumonia (continued). "Interestingly, inflammatory cytokines such as IL-1α and IL-8 may participate in the development of PIBO and ADV/MP infection-induced pneumonia." (PMID 40065384, 2025).
colorectal cancer (20 papers, 1998 to 2025). A primary or metastatic malignant neoplasm that affects the colon or rectum. "In head and neck cancer and colorectal cancer, IL-1α expression was associated with the promotion of malignant phenotypes." (PMID 37998338, 2023). "For instance, IL1A polymorphisms were found to be a risk factor for colorectal cancer in the Chinese Han population." (PMID 34931923, 2021). "The aim of this study was to assess the association of IL1A SNPs with the risk of colorectal cancer in a Chinese Han population." (PMID 30819119, 2019). "Highly expressed in human colorectal cancers, IL-1α is associated with poor prognosis." (PMID 39820336, 2025). "Besides IL-1α, IL-17A was linked with disease-free survival in patients with colorectal carcinoma (CRC), potentially serving as a surrogated marker in combination with CTC in CRC." (PMID 35966579, 2022). "This suggests that IL-1α is associated with liver metastasis of colorectal cancer." (PMID 34930323, 2021). "While IL-18, another member of the IL-1 family of cytokines, is dramatically lowered in CRC patients, IL-1α and IL-1β are significantly elevated, indicating a significant anti-tumourigenic effect in colorectal cancer." (PMID 38339377, 2024). "The colorectal cancer cell-derived IL-1α and rIL-1α significantly promoted CXCL12 expression by fibroblasts, and this enhancing effect can be significantly inhibited by IL-1Ra (P < 0.01)." (PMID 34930323, 2021). "IL-Ra can inhibit the tumor-promoting effect of CXCR4/CXCL12 signal in the microenvironment of colorectal cancer by antagonizing the secretion of IL-1α in colorectal cancer cells, and then inhibit the liver metastasis of colorectal cancer." (PMID 34930323, 2021). "Our previous studies have shown that IL-1α is one of the most important inflammatory cytokines involved in the metastasis of colorectal cancer, and plays an important role in the metastasis of colorectal cancer." (PMID 34930323, 2021). "Is there a correlation between autocrine IL-1α and paracrine CXCL12 in colorectal cancer, and does this association affect liver metastasis of colorectal cancer?" (PMID 34930323, 2021). "We further explored the relationship between IL-1α and the environment of colorectal cancer and its effect on metastasis, especially in angiogenesis." (PMID 34930323, 2021). "A recent study used HCT116 colorectal carcinoma cells as the research objects to depict the details of IL-1α-dependent protein-protein interactions (PPIs)." (PMID 32760201, 2020). "Both IL-1α and IL-16 are key players of inflammation and colorectal cancer development." (PMID 36771338, 2023). "IL-1α was expressed in high liver metastatic colorectal cancer cell lines (HT-29 and WiDr)." (PMID 34930323, 2021). "It promotes liver metastasis of colorectal cancer through IL-1α/PI3K/NF-κβ signal pathway." (PMID 34930323, 2021). "Together, these results suggested that the autocrine IL-1α and paracrine CXCL12 co-enhances the metastatic potential of colorectal cancer cells; IL-1Ra can inhibit the metastatic potential of colorectal cancer cells via decrease IL-1α/CXCR4/CXCL12 signaling pathways." (PMID 34930323, 2021). "Furthermore, palmatine inhibited the proliferation of human colorectal cancer cell lines by reducing the expression of the inflammatory cytokines IL-1a, IL1-b, and IL-8, granulocyte colony-stimulating factor, and granulocyte-macrophage colony-stimulating factor." (PMID 38732003, 2024). "For instance, MABp1, a true human moAb anti-IL-1α, showed disease control in patients with 18 different tumor types and its efficacy was further confirmed, in 2017, in a randomized, double-blind, placebo-controlled phase 3 study in a cohort of 333 advanced colorectal cancer patients." (PMID 32825489, 2020). "Autocrine IL-1α and paracrine CXCL12 co-enhances the metastatic potential of colorectal cancer cells; IL-1Ra can inhibit the metastatic potential of colorectal cancer cells via decrease IL-1α/CXCR4/CXCL12 signaling pathways." (PMID 34930323, 2021).
colorectal cancer (continued). "IL1A, another immune factor, is involved in downstream signaling activated by the IL1R1 receptor and thereby regulates a variety of tumor cells, such as cervical and colorectal cancer cells." (PMID 38025749, 2023). "RT-PCR and western blot revealed that IL-1α mRNA and protein were expressed by the higher liver-metastatic colorectal cancer cell lines HT-29 and WiDr, and not detected in low live-metastatic cell lines CaCo-2 and CoLo320." (PMID 34930323, 2021). "In conclusion, IL-1α and CXCL12 are not only important molecules in the interaction between colorectal cancer cells and tumor microenvironment, but also important cytokines affecting liver metastass of colorectal cancer." (PMID 34930323, 2021). "Furthermore, the high liver-metastatic colorectal cancer cell line (HT-29), which secretes IL-1α, significantly enhanced angiogenesis compared to the low liver-metastatic cell line (CaCo-2), which does not produce IL-1α (P < 0.01)." (PMID 34930323, 2021).
Insulin resistance (20 papers, 2010 to 2025). Increased resistance towards insulin, that is, diminished effectiveness of insulin in reducing blood glucose levels. "IL-1α is another important pro-inflammatory cytokine and has been linked with insulin resistance by inhibiting insulin signalling pathways." (PMID 25849717, 2015). "The insulin resistance in obese mice was associated with the increased expression of inflammatory markers Cd68, Il-6 and Il-1α; in contrast, most of these genes were down-regulated in CR mice." (PMID 20307313, 2010). "To clarify the causality relationship between cytokines IL-1α, IL-1β and IL-6 from macrophages and insulin resistance, we co-cultured primary hepatocytes with BMDMs and treated them with different combinations of insulin, TSH, IL-1 blocker IL-1RA or IL-6 blocker IL-6ST." (PMID 40523992, 2025). "Inflammatory cytokines, e.g., IL-1family members (IL-1α, IL-1β, IL-1Rα, IL-18, IL-33, IL-36, IL-37, and IL-38), are associated with the regulation of atherosclerosis, insulin resistance, and adipose tissue inflammation, all of which are common features of NAFLD." (PMID 31597283, 2019). "Collectively, our data indicate that TSH activates inflammatory signaling and promotes the secretion of IL-1α, IL-1β and IL-6 in macrophages, thus aggravating insulin resistance." (PMID 40523992, 2025). "It has been also shown that obese individuals experience an increase in pro-inflammatory IL-1α and IL-1β, which consequently lead to insulin resistance." (PMID 37180128, 2023). "Although IL-1β is a potent accelerator of chronic inflammation in adipose tissues that plays a central role in pathogenesis of insulin resistance, IL-1Ra exerts an anti-inflammatory effect by blocking the action of IL-1α and IL-1β on the IL-1 receptor." (PMID 31509948, 2019). "There is a possibility that differences in blood glucose levels seen in CX3CR1−/− and IL-1a/b KO mice compared to WT following insulin administration are rather due to insulin resistance than impaired counterregulatory responses." (PMID 30996341, 2019). "IL-1α, IL-1β, and oxidative stress also induce insulin resistance by modulating IR or IRS-1 phosphorylation." (PMID 31581253, 2019). "In adipose tissue, we detected increases in IL-1α, a key cytokine that signals through the IL-1R1 and likely contributes to inflammatory responses relevant to insulin resistance." (PMID 29038790, 2017). "BAT-derived IL-1α and in particular IL-6 are critical pro-inflammatory cytokines in the induction of insulin resistance and activation of the immune system." (PMID 26795216, 2016). "Only a few studies have examined the role of IL-1α as a mediator for cellular insulin resistance in sharp contrast to a number of reports on IL-1β." (PMID 22216303, 2011). "Interestingly, six of the cytokines elevated in 3n mice that were attenuated with the Ch+ diet (IL-1α, IL-1β, IFN-γ, TNF-α, IL-3, and IL-6) have been associated with the development of insulin resistance in T2D." (PMID 39683562, 2024). "We speculate that lower IL-1α levels in our GDM offspring might have exerted protection against the manifestation of insulin resistance and the development of adiposity." (PMID 36717684, 2023). "Insulin resistance is associated with an increase of TNF-α, IL-1α, IL-1β, IL-6, and leptin." (PMID 34970568, 2021). "In individuals with NAFLD, lipotoxicity, insulin resistance, and endotoxins trigger the activation of proinflammatory cytokines such as tumor necrosis factor-α (TNF-α), interleukin-1α (IL-1α), interleukin-1β (IL-1β), interleukin-6 (IL-6), and resistin." (PMID 39275255, 2024). "Mechanistically, increased TSH levels in subclinical hypothyroidism promoted the secretion of cytokines IL-1α, IL-1β and IL-6 by inducing macrophage M1 polarization, which upregulated EGR1 to transcriptionally activate LCN2 and SOCS3 in insulin target cells, thereby exacerbating insulin resistance." (PMID 40523992, 2025).
myocardial infarction (20 papers, 2010 to 2025). Gross necrosis of the myocardium, as a result of interruption of the blood supply to the area, as in coronary thrombosis. "IL-1α, identified as a pivotal regulatory factor in the inflammatory processes associated with myocardial infarction and CKD, demonstrates a significant correlation with the incidence of cardiovascular events." (PMID 38558798, 2024). "The individual roles of IL-1α vs. IL-1β in the setting of acute myocardial infarction (AMI) and CKD were investigated in patients and knockout mice deficient for IL-1α vs. IL-1β." (PMID 40486517, 2025). "IL1A is detectable in mouse cardiomyocytes and induce inflammation in heart after acute myocardial infarction (AMI), which can be mitigated by Il1a knockout." (PMID 39168969, 2024). "Recent investigations reveal an upregulation in the surface expression of IL-1α on monocytes in individuals afflicted with acute myocardial infarction (AMI) and CKD." (PMID 38558798, 2024). "Excluding the effect of IL-1α signalling is an important consideration, as IL-1α released from dying cells promotes sterile inflammation and leukocyte recruitment, and ablation of IL-1α alleviates inflammation in myocardial infarction." (PMID 28438165, 2017). "In cardiac myofibroblasts, the proinflammatory cytokine interleukin-1α (IL-1α), a core inflammatory mediator following myocardial infarction (post-MI), paradoxically downregulates ADAMTS1 expression at both mRNA and protein levels." (PMID 41440846, 2025). "IL-1α and IL-1β are both agonists of the IL1R; IL-1α is released by necrotic cardiomyocytes and functions as an alarm signal, triggering a postinfarction inflammatory reaction, while IL-1β is produced by the leukocytes invading the infarct area after myocardial infarction." (PMID 33513892, 2021). "It has been hypothesized that IL-1α is released from damaged cardiomyocytes following myocardial infarction (MI) and activates cardiac fibroblasts via its receptor (IL-1R1) to drive the early stages of cardiac remodeling." (PMID 31393855, 2019). "Fibroblast-specific knockout of IL-1R1, but not cardiomyocyte-specific knockout of IL-1α, improved cardiac function and remodeling after myocardial infarction." (PMID 31393855, 2019). "Furthermore, in a mouse model of myocardial infarction, TNF-α mRNA, IL-1α, IL-2, IL-4, IL-5, IL-6, IL-10, IL-17A, TNF-α, IFN-γ, and GM-CSF expression were all lower in the infarct area of TLR4-deficient mice compared with wild-type mice." (PMID 30399158, 2018).